Y_RNA (Y RNA )
Gene: Miscellaneous RNA gene on chromosome 3 (152,449,272 to 152,449,384, forward strand). Ensembl gene ENSG00000201217.
Homologues: Orthologues: chimpanzee Y_RNA (99% identical), macaque Y_RNA (90% identical). Paralogues in human: RNY1 (86% identical), Y_RNA (86% identical), Y_RNA (85% identical), RNY1P11 (84% identical), Y_RNA (84% identical), Y_RNA (83% identical), Y_RNA (82% identical), Y_RNA (81% identical), RNY1P5 (81% identical), RNY1P8 (81% identical), Y_RNA (80% identical), RNY1P10 (79% identical), and 96 more.